MTAP (methylthioadenosine phosphorylase)
Diseases named in the same sentence as MTAP in open-access papers (continued):
Sharing a sentence is not in itself a finding about the gene and the disease.
breast carcinoma (26 papers, 2009 to 2025). "In the COSMIC gene database, MTAP copy number variation loss was reported in 2.55% (38/1492) breast cancer samples." (PMID 36913304, 2023). "The significant difference in MTAP activity between tumor and host cells ensures a high level of treatment selectivity, making it a promising therapy for MTAP deficient malignancies in general, and MTAP deficient breast cancer." (PMID 36913304, 2023). "In patients with breast cancer, MTAP deficiency is associated with poor survival outcomes." (PMID 37091983, 2023). "The co-occurrence of CDKN2A/MTAP deletion may explain early literature that observed MTAP loss in leukaemia and breast cancer." (PMID 37795443, 2023). "This is especially significant for breast cancer patients as MTAP deletion, a trait conferring synthetic lethality with single agent second-generation PRMT5 inhibitors is rarely observed." (PMID 39695328, 2025). "Silencing of MTAP in a breast cancer cell line activates ornithine decarboxylase (ODC) activity elevating polyamines synthesis and promoting orthotopic xenograft tumor growth and metastasis." (PMID 39941901, 2025). "Although literature on MTAP loss in breast cancer is scarce, MTAP and CDKN2A loss co-occur with concordance in up to 90% of the cases, enabling indirect estimation of MTAP loss." (PMID 36913304, 2023). "Cytotoxicity assays with inhibitors of de novo adenine synthesis, 5-fluorouracil (5-FU), methotrexate (MTX) and 5′aza-deoxycytidine (AZA) after MTAP gene knockdown in breast cancer cell lines have shown an increased sensitivity to 5-FU." (PMID 36913304, 2023). "In breast cancer, MTAP downregulation activates ornithine decarboxylase (ODC) which in turn leads to formation of putrescine which promotes tumor migration, invasion and angiogenesis." (PMID 36913304, 2023). "Emerging studies show that MTAP overexpression dramatically changes the amounts of polyamine metabolites (particularly putrescine) in breast cancer cells." (PMID 36913304, 2023). "Deletion of the key catalytic enzyme methylthioadenosine phosphorylase (MTAP) gene is associated with the sensitivity of GSK3368715,331 and a current phase II clinical study of GSK3368715 in breast cancer has been enrolled (NCT04676516)." (PMID 37699892, 2023). "The aim of the present study was to characterize MTAP expression in breast cancer patients and cell lines and examine the relationship between MTAP expression and chemo-sensitivity to inhibitors of AMP synthesis." (PMID 26751376, 2016). "This work investigated MTAP expression in breast cancer patients and cell lines, and examined the relationship between MTAP expression and chemo-sensitivity to inhibitors of AMP synthesis." (PMID 26751376, 2016). "Expression of MTAP mRNA was also evaluated in FFPE breast cancer samples MTAP mRNA level was 1.62 times greater in Luminal-A than in TNBC, and this difference was statistically significant (p value< 0.0001)." (PMID 26751376, 2016). "Here, we characterized gene expression (mRNA and protein levels) of MTAP and CDKN2A in seven breast cancer cell lines and performed a promoter methylation analysis of MTAP." (PMID 26751376, 2016). "In MTAP-null breast cancers, an increased amount of putrescine led to enhanced metastatic activity." (PMID 41439984, 2025). "MTAP is downregulated in various human cancers and appears to be deleted in many breast cancers." (PMID 39941901, 2025). "Similarly, 5′-methylthioadenosine phosphorylase (MTAP) plays a critical metastasis inhibitory role in breast cancer by inhibiting ODC activity." (PMID 38650895, 2024). "However, uncertainty still exists regarding MTAP’s clinical and biological impact on breast cancer metastasis." (PMID 36913304, 2023). "Since elevated expression of CHAF1A may cause accumulation of MTA via regulating amino acid metabolism, it is possible that purine analogue might be potential treatment option in MTAP deletion breast cancer patient with higher expression of CHAF1A." (PMID 36968583, 2023).
breast carcinoma (continued). "Vieira de Oliveira also evaluated MTAP expression in two groups of breast cancer patient samples, including fresh tumors and paired normal breast tissue, as well as formalin-fixed paraffin embedded (FFPE) core breast cancer samples diagnosed as Luminal-A tumors and TNBC." (PMID 36913304, 2023). "In the AACR GENIE portal, MTAP deletion was reported in 2.9% (138/15210) breast cancer specimens." (PMID 36913304, 2023). "It has been demonstrated that MTAP expression could abrogate a series of malignant behaviors of breast cancer cells, including tumor angiogenesis, tumor growth and metastasis." (PMID 37091983, 2023). "The MTAP gene is located at 9p21, a chromosome region often deleted in breast cancer (BC)." (PMID 35541910, 2022). "Despite a previous report showing an inhibitory effect of MTAP on breast cancer cell growth, the functional roles of MTAP in lung cancer remain unclear." (PMID 35766227, 2022). "mRNA, protein and methylation status of CDKN2A and MTAP in the breast cancer cell lines." (PMID 26751376, 2016). "MTAP expression was also evaluated in two groups of samples from breast cancer patients, fresh tumors and paired normal breast tissue, and from formalin-fixed paraffin embedded (FFPE) core breast cancer samples diagnosed as Luminal-A tumors and triple negative breast tumors (TNBC)." (PMID 26751376, 2016). "MTAP mRNA levels were evaluated in seven breast cancer cell lines." (PMID 26751376, 2016). "We performed MS-PCR in breast cancer cell lines to evaluate the MTAP promoter status." (PMID 26751376, 2016). "Functionally, MTAP reexpression in MTAP-deleted breast cancer cells may inhibit anchorage-independent growth and in vivo tumorigenicity." (PMID 25426549, 2014). "MTAP loss is associated with ER-, HER2- and TNBC status, features a distinctive GL with potential to impact both targeted and immunotherapies and enables emerging clinical trials testing MTA2 and PRMT5 inhibitors for patients with clinically advanced breast cancer." (PMID 36913304, 2023). "Similarly, our study also showed for the first time that low expression of MTAP was positively correlated with tumor recurrence in BC patients, suggesting that MTAP may play an important role in the malignant progression of breast cancer." (PMID 35541910, 2022). "Nevertheless, there is a lack of information on MTAP-deficiency in primary breast cancer." (PMID 26751376, 2016). "Bone cancers, breast cancers, HCC, and colorectal cancers are some others that have reported less than a 10% frequency of homozygous MTAP deletion." (PMID 41439984, 2025). "All of these phenotypes support the idea that MTAP is a tumor suppressor gene and are consistent with our previous study that MTAP acted as a tumor suppressor gene in a MCF-7 breast cancer cell line." (PMID 25387827, 2014). "The list of these genes includes not only a large number of known breast cancer genes (e.g. CDH1, CDH3, BMP4, MTAP, CDKN2B), revealed by previous studies using breast tumor tissues and breast cancer cell lines but also novel genes." (PMID 24885402, 2014). "Breast cancers (Multimedia Appendix 2) have 65 breakpoints strictly within this interferon-MTAP region (21,579,478‐20,503,534 on chromosome 9), not counting longer fragments that include the interval." (PMID 39885374, 2025). "Herein, MTAP status is tightly related to the metastatic potential of BC cells by affecting ODC activity, which may provide promising therapeutic strategies for breast cancer." (PMID 37091983, 2023). "This study showed that, in an orthotopic breast cancer model using BT20 cells, MTAP downregulation could greatly accelerate both tumor development and metastasis." (PMID 36913304, 2023). "We analyzed MTAP and CDKN2A gene (RT-qPCR) and protein (western-blotting) expression in seven breast cancer cell lines and evaluated their promoter methylation patterns to better characterize the contribution of these genes to breast cancer." (PMID 26751376, 2016).
breast carcinoma (continued). "The overexpression of lnc-MTAP (CDKN2B-AS1), lnc-PCP4 (DSCAM-S1), and lnc-FAM (H19) in breast cells suggests that these lncRNAs may have significant role to play in breast cancer." (PMID 30159409, 2016). "Some regions statistically associated with grade III tumors in our study harbor genes either frequently amplified in aggressive breast cancer such as the oncogenes MYC (8q24) and CCNE1 (19q12) or already reported as deleted in breast tumors such as MTAP (9p21)." (PMID 25391423, 2015). "Information on the incidence of MTAP-deficiency in breast cancer is still limited, but of nine cell lines tested, four, including the often-studied MCF-7 and MDA-MB-231, were MTAP-negative." (PMID 19478948, 2009). "Interestingly, in vivo study showed that downregulation of MTAP could significantly promote both tumor growth and metastasis in BT20 cell-implanted orthotopic breast cancer model." (PMID 35541910, 2022). "Taken together, our data suggested that MTAP has a critical metastasis-suppressive role by tightly regulating ODC activity in BC cells, which may serve as a prominent novel therapeutic target for advanced breast cancer treatment." (PMID 35541910, 2022).
lung cancer (25 papers, 2014 to 2026). A malignant neoplasm involving the lung. "Repression of MTAP‐dependent symmetric dimethylation mediated by PRMT5 increases vimentin protein stability and leads to invasion and metastasis in MTAP‐deficient lung cancer." (PMID 35766227, 2022). "In this study, we verify the significance of vimentin in metastasis promotion of MTAP‐deficient lung cancer." (PMID 35766227, 2022). "Herein, we investigated the role of MTAP in lung cancer metastasis, and elucidated its underlying mechanisms by using a methylproteomic screen." (PMID 35766227, 2022). "Clinically, approximately 15% of lung cancer patients carry MTAP gene deletion, and cancer cells with MTAP loss exhibit an increase of intracellular levels of MTA." (PMID 35766227, 2022). "Other studies have also shown the association of MTAP with different cancers such as head and neck carcinoma, lung cancer, prostate, colorectal, and breast cancer." (PMID 36572880, 2022). "The suppressed expression of MTAP predominantly contributed to the oncogenic signaling in CDKN2A‐deficient lung cancer." (PMID 33155773, 2020). "In clinical, blockades of de novo purine synthesis achieved favorable results in parts of MTAP-deficient tumors, but the role of MTAP expression still have some unclear in lung cancer." (PMID 31965001, 2020). "Mechanistically, we identified MTAP as a positively correlated gene with CDKN2A in lung cancer, which was significantly downregulated in CDKN2A‐deficient cells." (PMID 33155773, 2020). "Similarly, MTAP loss was found to upregulate immune checkpoint protein programmed cell death ligand 1 (PD-L1) in lung cancers, for subsequent inhibition of T-cell activity." (PMID 41439984, 2025). "MTAP loss has also been reported in 17.1% of gastrointestinal (GI) tumors and 15% of lung cancers." (PMID 41439984, 2025). "MTA in turn inhibits PRMT5, supporting the hypothesis that MTAP deficient lung cancer may respond better to PRMT5 inhibition." (PMID 35747993, 2023). "A common PRMT dysregulation, specifically of PRMT5, has been correlated with the loss of MTAP (5-methylthioadenosine phosphorylase) expression in lung cancer, resulting in the accumulation of methylthioadenosine (MTA), which significantly inhibits PRMT5 activity." (PMID 38001653, 2023). "Currently, MTAP‐loss NSCLC represents a histologically heterogeneous group of lung cancers." (PMID 35747993, 2023). "However, the detailed molecular events underlying the positive correlation between CDNK2A and MTAP in the context of lung cancer is yet to be defined." (PMID 33155773, 2020). "We next performed targeted metabolomics analysis to verify the catalytic activity of ectopically expressed MTAP in lung cancer cells." (PMID 35766227, 2022). "In an orthotopic xenograft model, smaller primary tumors and less metastatic tumor nodules were observed in mice receiving MTAP‐overexpressing cells, indicating that MTAP inhibits the metastatic potential of lung cancer." (PMID 35766227, 2022). "Homozygous deletion of the MTAP gene is frequently (~ 40%) seen in lung cancer patients, and leads to elevated levels of MTA, a metabolite known to act as an endogenous inhibitor of PRMT5 activity." (PMID 33691794, 2021). "Most importantly, here, we further identified a positive correlation between CDKN2A and Methylthioadenosine Phosphorylase (MTAP, OMIM association number, 156540) in lung cancer." (PMID 33155773, 2020). "Our results also highlighted the predominant roles of MTAP in mediating the antitumoral activities of CDKN2A in lung cancer cells." (PMID 33155773, 2020). "In addition, MTAP mRNA expression was almost undetectable in 42.9% (6/14) of all tested lung cancer cell lines in our lab (Fig EV1B)." (PMID 35766227, 2022). "A third recent study reported that 9p21.3 loss (as assessed by CDKN2A, CDKN2B plus MTAP) was associated with poor survival after anti-PD-1 monotherapy but not in ICT–chemotherapy combination treated patients with nonsquamous lung cancer." (PMID 36395141, 2022).
lung cancer (continued). "Therefore, our data clearly suggested that MTAP predominantly mediated the tumor suppressor roles of CDKN2A in lung cancer." (PMID 33155773, 2020). "In view of the complex regulatory network involved in cell cycle control elicited by CDKN2A deficiency, we hypothesized that MTAP might function indirectly and at the downstream of CDKN2A in lung cancer." (PMID 33155773, 2020). "Mechanistically, we unraveled that MTAP, which was positively correlated with CDKN2A, predominantly mediated the antitumoral function of CDKN2A in lung cancer." (PMID 33155773, 2020). "MTA-induced protein methyltransferase (PRMT) inhibition and lack of symmetric dimethyl arginine (SDMA) activity in MTAP-null lung cancers leads to reduced degradation of vimentin and increased metastatic activity." (PMID 41439984, 2025). "Supporting evidence that MTDIA could enhance anticancer effects even in MTAP−/− genotypes is found by comparing tumor growth inhibition by single-agent MTDIA treatment in MTAP+/+ and MTAP−/− lung carcinoma cell lines in vivo." (PMID 38000655, 2024). "Indeed, the ubiquitination of Vimentin influenced by symmetric dimethylarginine (sDMA) is thought to be necessary for the roles of MTAP and PRMT5 in lung cancer metastasis." (PMID 36969045, 2023). "MTAP and PRMT5 negatively correlate with vimentin in lung cancer samples." (PMID 35766227, 2022).
non-small cell lung carcinoma (19 papers, 2011 to 2026). A group of at least three distinct histological types of lung cancer, including non-small cell squamous cell carcinoma, adenocarcinoma, and large cell carcinoma. "In MTAP-deficient non-small cell lung cancer, the type I PRMT inhibitor MS023 combined with the PARP inhibitor talazoparib induces greater DNA damage and significantly reduces cell viability." (PMID 41204384, 2025). "Loss of mTAP expression was also reported in other neoplasms, including 21% of non-small cell lung cancers." (PMID 35565429, 2022). "In a retrospective study, 99 non-small cell lung cancer patients treated with surgery were collected to explore the correlation of MTAP and survival." (PMID 31965001, 2020). "In some rare cases associated with non-small-cell lung cancer and some other cancers MTAP loss occurred in absence of CDKN2A deletion." (PMID 36572880, 2022). "Solid tumors frequently lacking MTAP include MPM, non-small cell lung cancer (NSCLC), gliomas and pancreatic cancer." (PMID 30123503, 2018).
leukemia (17 papers, 2009 to 2025). A malignant (clonal) hematologic disorder, involving hematopoietic stem cells and characterized by the presence of primitive or atypical myeloid or lymphoid cells in the bone marrow and the blood. "After Toohey found that some murine leukemia cell lines lack MTAP, others reported that many of the most common human tumors are also deficient in MTAP." (PMID 19478948, 2009). "MTAP-deleted and MTAP-rescued cells were co-cultured with suspended leukemia MV-4-11 (monomyelocytic leukemia, macrophage-like) cells in DMEM." (PMID 34244484, 2021). "Loss of methylthioadenosine phosphorylase (MTAP), the first enzyme in the salvage pathway, is often observed in cancers including NSCLC, leukemia, and GBM." (PMID 32824193, 2020). "There has been much research on the effect of MTAP expression on different leukemia and lymphoma types, and there is still much more information to uncover regarding the best drugs and optimal dosages to use when treating patients." (PMID 25917288, 2015). "In addition, MAT2A has been identified as a critical enzyme in CSCs, MLL-r leukemias, and cancers that lack methylthioadenosine-phosphorylase (MTAP), which accounts for 15% of all cancers." (PMID 38643304, 2024). "Furthermore, we found that the co-culture of MTAP-deleted cells with suspended MTAP-WT leukemia cells (MV-4-11, myeloid-like) resulted in higher SDMA levels—indicating higher PRMT5 activity and lower intracellular MTA levels—compared to the monoculture MTAP-deleted cells." (PMID 34244484, 2021). "MTA was shown to be secreted into culture medium by MTAP-negative leukaemia cells in vitro, whilst elevated levels of MTA and MTA secretion have frequently been observed in multiple cell lines derived from solid tumours with homozygous deletion of MTAP." (PMID 37795443, 2023). "The study presented here provides a strong rationale for using the combination of pralatrexate and 6-thioguanine for the treatment of leukemias and lymphomas lacking MTAP." (PMID 25917288, 2015). "These MTAP deletions could be exploited as alternative therapy in MTAP-negative OS patients with the use of 6-thioguanine (6-TG), showing good results in leukemia or in metastatic prostate cancer models, or other inhibitors of de novo purine synthesis." (PMID 35884563, 2022).